IL6 (interleukin 6)
Diseases named in the same sentence as IL6 in open-access papers (continued):
Sharing a sentence is not in itself a finding about the gene and the disease.
type 2 diabetes (continued). "Their results showed that the levels of IL-6 were significantly higher in type 2 diabetes with diabetic nephropathy as compared to the non-DN group." (PMID 36363561, 2022). "Last but not least, no measures of inflammatory proteins such as CRP or IL-6 were used in the analysis, and clinical conditions such as hypertension and type 2 diabetes should be further explored." (PMID 36713451, 2022). "They concluded that serum IL-6 levels increased in type 2 diabetics with nephropathy in comparison to the diabetics without nephropathy." (PMID 36363561, 2022). "An increase in plasma IL-6 levels is associated with decreased TFAM protein production in liver biopsies in obese patients with and without type 2 diabetes." (PMID 33579000, 2021). "Curcumin could improve endothelial function and reduce oxidative stress and levels of inflammatory markers (IL-6, TNF alpha, endothelin-1) in type 2 diabetes patients and enhance the functions of β cells." (PMID 34069726, 2021). "Therefore, further researches are needed to have a broader vision about cinnamon intake on plasma level of NF-kB, SIRT1 and systemic inflammation factors including hs-CRP, IL-6 and TNF-α in type 2 diabetes patients." (PMID 31901246, 2020). "IM patients with type 2 diabetes (main group) have a 2.7 times increase in CRP content, 4.4 and 3.1 times in proinflammatory IL-6 and TNF-α, respectively, as well as anti-inflammatory IL-10 concentration of 1.9 times higher relative to the indicators in the control group." (PMID 32341698, 2020). "In a study of 367 Mexican–Americans, type 2 diabetes was strongly related to elevated levels of IL-6, leptin, CRP and TNF-α, whereas higher glucose levels correlated positively and linearly with high levels of IL-6 and leptin." (PMID 32751810, 2020). "When we did subgroup analyses, we found a significant reducing effect of vitamin E on serum levels of IL-6 and CRP in studies performed on subjects with insulin resistance-related disorders including type 2 diabetes, metabolic syndrome, and non-alcoholic fatty liver disease." (PMID 33057114, 2020). "Thus, measurement of circulating sRAGE and IL-6 level can aid the prediction and/or diagnosis of CRC in middle-aged and older type 2 diabetes patients." (PMID 33187505, 2020). "In type 2 diabetic patients, sitagliptin treatment reduced the molecular markers of inflammation as CRP and IL-6 in mononuclear cells, as well as circulating levels of TNF-α, IL-1β, IL-6, intracellular adhesion molecules and CRP." (PMID 32848769, 2020). "Elevated levels of IL-6 and CRP have been shown to predict the development of type 2 diabetes." (PMID 28813433, 2017). "In fact, a rise in inflammatory markers such as C-reactive protein (CRP), haptoglobin, and fibrinogen in the blood is recognized in diabetic patients, and increases in interleukin- (IL-) 1β, IL-6, and CRP in the blood are predictive factors for type 2 diabetes." (PMID 28168013, 2017). "Furthermore, various longitudinal studies have shown that elevated levels of CRP, IL-1β, IL-6, and TNF-α predict the development of type 2 diabetes." (PMID 27034691, 2016). "Lowering resistin by RNA oligo with reduction of circulating TNF-α and IL-6 might provide a new insight into managing inflammation-mediated diseases, such as NAFLD, type 2 diabetes, and cardiovascular disease." (PMID 25922835, 2015). "High levels of IL-6, TNF-α receptor 2 and CRP predicted incident type 2 diabetes." (PMID 25722960, 2015). "It is noteworthy that the concentration of CRP, IL-6 and TNF observed in this study appeared to be slightly larger than the values found in Chinese patients with type 2 diabetes or coronary heart disease and in the prospective Multi-Ethnic Study of Atherosclerosis." (PMID 26080804, 2015). "High levels of IL-6 and CRP predicted incident type 2 diabetes." (PMID 25722960, 2015).
type 2 diabetes (continued). "Some studies concluded that IL-6 levels, but not CRP or fibrinogen levels, add significantly to the prediction of macrovascular events and mortality in individuals with type 2 diabetes who have baseline CVD or risk factors." (PMID 24955583, 2014). "In the LPS study, patients with type 2 diabetes and healthy controls were administered an LPS bolus of 0.3 ng/kg, which induced an inflammatory response with increased body temperature, heart rate, neutrophil count, and TNF-α and IL-6 levels." (PMID 25104880, 2014). "It was demonstrated that CTB-APSL fusion protein could effectively improve the inflammatory response in type 2 diabetic mice by reducing the levels of the inflammatory cytokines TNF-α and IL-6." (PMID 24633252, 2014). "Furthermore, recent studies in patients with type 2 diabetes showed that insulin treatment decreased expressions of inflammatory cytokines, such as MCP-1, ICAM-1, soluble VCAM-1 (sVCAM-1), TNF-α, and IL-6." (PMID 23862164, 2013). "All of the pro-inflammatory cytokines evaluated (IL-1β, IL-6, IL-8, IL-10, IL-12p70, and TNF-α) were increased in patients with type 2 diabetes, although only the increases in TNF-α, IL-8, and IL-12 p70 were statistically significant in comparison to healthy individuals (P < 0.05)." (PMID 22500980, 2012). "Further analysis of this putative atorvastatin-response subgroup showed characteristics of systemic subclinical inflammation as seen in type 2 diabetes, increased BMI, higher levels of fasting C-peptide and, besides CRP, higher systemic concentrations of IL-6, IL-1RA, sICAM-1 and E-selectin." (PMID 22448235, 2012). "Therefore, to further evaluate the potential consequences of IL-6 resistance in type 2 diabetes, we assessed AMPK activity in response to 30 and 60 minutes of exposure to recombinant IL-6 in He myocytes and DM myocytes." (PMID 22761857, 2012). "This is the first study to show that controlling post-meal hyperglycaemia with a prandial + basal insulin regimen vs. a basal insulin regimen can attenuate the meal-induced increases in hsCRP, interleukin-6 and TNF-α in patients with Type 2 diabetes on metformin." (PMID 21517955, 2011). "The cascade of TNF-α and IL-6 elevation leads to increments in hsCRP and fibrinogen, with resulting adhesion molecule expression, and may facilitate development of type 2 diabetes mellitus (T2DM) as well as CHD." (PMID 22482065, 2011). "Studies of type 2 diabetes, in the absence of HIV infection, have observed associations between inflammatory markers such as IL-6 and CRP and degree of albuminuria." (PMID 21931772, 2011). "Blood levels of IL-6, but not TNFα have also been reported to be an independent predictor of type 2 diabetes after adjustment for BMI." (PMID 20525188, 2010). "Since serum levels of MCP-1 are elevated in patients with type 2 diabetes, as are levels of TNF-α and interleukin-6, it is conceivable that diabetics mount an exaggerated immune response to C. neoformans (paradoxical to their defective immune state) leading to fatal outcomes." (PMID 19946453, 2009). "We have demonstrated that resistin mRNAexpression from human peripheral monocyte-enriched mononuclear cells iselevated in type 2 diabetic women, compared to healthy control women, inparallel with significant increases in mononuclear IL-1β, TNF-α, and IL-6 mRNAexpression." (PMID 19125180, 2008). "Our study provides a comprehensive biochemical and immunological profile, simultaneously assessing BDNF, vitamins D, B12, folic acid, zinc, calcium, IL-6, and IL-12, in well-matched groups of type 2 diabetic patients with and without nephropathy, as well as healthy controls." (PMID 41142318, 2025).
type 2 diabetes (continued). "In patients with type 2 diabetes and CKD, a post hoc analysis of the DELIGHT trial reported that changes in TSAT and transferrin over 24 weeks of treatment with dapagliflozin correlated with changes in urinary and plasma interleukin-6, an inflammatory cytokine that regulates hepcidin expression." (PMID 39304530, 2025). "Furthermore, plasma IL-6 levels were similar between groups, suggesting that IL-6 is not hypersecreted into the circulation during SP-induced type 2 diabetes." (PMID 38561446, 2024). "Even slight elevations in IL-6 and CRP levels, which may not manifest clinically, can heighten the risk of developing heart disease and type 2 diabetes in individuals who were previously considered healthy." (PMID 39685657, 2024). "The link between resistin, type II diabetes mellitus and inflammation has been demonstrated, whereby higher plasm resistin and IL-6 levels were noted in patients with diabetic foot ulceration compared with patients with type II diabetes mellitus and no foot ulceration." (PMID 36983885, 2023). "Elevated levels of interleukin-1β (IL-1β), interleukin-6 (IL-6), interleukin-8 (IL-8), tumor necrosis factor α (TNF-α), soluble interleukin-2 receptor (sIL-2R), and nitric oxide (NO) correlating with both the presence and the severity of DR were found in the serum of patients with type 2 diabetes." (PMID 36012690, 2022). "Substituting one serving of red meat with one serving of legumes in DASH diet, at least five days a week, could improve the hs-CRP, TNF-α, IL-6, and MDA in participants with type 2 diabetes regardless of having rs7903146 risk or non-risk allele." (PMID 35585604, 2022). "In conclusion, substituting one serving of red meat with one serving of legumes in DASH diet, at least five days a week, could improve the hs-CRP, TNF-α, IL-6, and MDA in participants with type 2 diabetes regardless of having rs7903146 risk or non-risk allele." (PMID 35585604, 2022). "Evidence indicate that inflammation and, in particular, high levels of TNF-α, IL-β and IL-6 are factors involved in the development of type-1 diabetes, and TNF- α, IL-1, IL-6, IL-10, leptin, and adiponectin are the factors involved in the development of type-2 diabetes." (PMID 36011116, 2022). "Additionally, our results revealed that B. vernae extract or metformin treatment for 30 days significantly decreased (P < 0.01) serum FBG, INS, HOMA-IR, GSP, TNF-α, IL-1β, and IL-6 levels, whereas increased serum ISI levels (P < 0.01) in type 2 diabetic rats, compared with the model group." (PMID 32636751, 2020). "Our results revealed that the levels of TNF-α, IL-6, and MCP-1 were observably decreased after the administration of JQJT tablets, which indicated that JQJT tablets could inhibit the inflammatory reaction in type 2 diabetes." (PMID 30733971, 2019). "Nowadays PCOS is considered a low grade chronic inflammation state, with high serum levels of tumor necrosis factor - α (TNF-α), interleukin-6 and CRP, that could be the link between PCOS and its long-term complications like type 2 diabetes and cardiovascular disease." (PMID 30850700, 2019). "As far as the literature could be evaluated, it was shown for the first time in our study that serum IL-6 levels were effective for the discrimination of infected and noninfected ulcer in a study including only type 2 diabetes patients." (PMID 29675434, 2018). "However, a chronic increase in inflammatory markers, such as interleukin (IL)-6, IL-1, tumor necrosis factor α (TNF-α), and C-reactive protein (CRP), plays a key role in various chronic conditions (e.g., type 2 diabetes mellitus [T2DM], cardiovascular diseases [CVDs], and cancer)." (PMID 29495330, 2018). "Furthermore, they evaluated the protective effects of flavone, fisetin, morin, or tricetin on expression of pro-inflammatory cytokines, such as IL-6 and TNF-α, using an ex vivo system after procurement of blood samples from healthy men and patients with COPD and type 2 diabetes (T2D)." (PMID 28974953, 2017).
type 2 diabetes (continued). "CRP is regarded as a reliable down-stream marker of inflammation, and although IL-6 is suggested to be one of its main inducers, we could not find any association of CRP with CV events and death in this population with type 2 diabetes." (PMID 23987834, 2013). "In JNK-deficient mice, the expression of proinflammatory cytokines (including TNFα, IL-6, and MCP-1) induced by obesity is suppressed, and this can promote protection from insulin resistance and T2DM (type 2 diabetes mellitus)." (PMID 23762873, 2013). "In addition, it was also noted that TGFBR1 (transforming growth factor-β receptor 1), which is an anti-inflammatory cytokine that inhibits the production of pro-inflammatory cytokines such as IL-6 and TNF-α was found to be up regulated in type 2 diabetes, most probably as a compensatory mechanism." (PMID 18078524, 2007). "Interestingly, serum levels of IL-6 (r=0.21, p<0.05), sIL-6R (r=0.31, p<0.01) and sgp130 (p=0.35, r<0.01) were positively correlated with age, a correlation that we had previously not observed for these proteins in type 2 diabetes patients." (PMID 39835136, 2024). "In addition, a significant increase in Gram-negative bacteria is also found in type 2 diabetes and CKD patients, which contain LPS in the outer membrane and are associated with the elevation of inflammatory biomarkers such as TNF-α, IL-6, and C-reactive protein (CRP) in fecal microbiota samples." (PMID 37362429, 2023). "Although the effect of dapagliflozin on serum IL-6 was not significant in DELIGHT, the effect size was similar to data from a larger clinical trial with canagliflozin demonstrating a 5% decrease in plasma IL-6 in patients with type 2 diabetes at high cardiovascular risk." (PMID 38017482, 2023). "Interestingly, we have previously demonstrated that monocyte-enriched mononuclear cells from individuals with type 2 diabetes show increased levels of visfatin, resistin, TNF-α, IL-6, and IL-1β mRNA expression indicating that hyperinsulinemia and hyperglycemia could enhance cytokine production." (PMID 23484124, 2013). "However, we could not address the association between inflammation and type 2 diabetes because most study subjects did not have available measurements of inflammatory markers such as CRP and IL-6." (PMID 22524685, 2012). "This is in accordance with previously published report highlighting those patients with type 2 diabetes treated with IL-1β-inhibitors exhibit reductions in hs-CRP and IL-6 without changes in HbA1c." (PMID 38725572, 2024). "Metformin has previously been shown to decrease circulating levels of CRP, IL-6, and TNF-α in patients with type 2 diabetes, however this finding was not replicated in our subjects who were nondiabetic and nonprediabetic." (PMID 37131271, 2023). "The purpose of this research is to study the dynamics of C-reactive protein (CRP), IL-6, TNF-α, and interleukin-10 (IL-10) in patients with type 2 diabetes who underwent non-Q-myocardial infarction (non-Q-IM), against the background of ALA." (PMID 32341698, 2020). "This study elucidated that cinnamon supplementation has no beneficial effects in reduction of NF-kB, SIRT1, hs-CRP, IL-6 and TNF-α levels in type 2 diabetes patients which have a considerable role in development of atherogenesis." (PMID 31901246, 2020). "In the current study, where all women had a history of GDM, those who developed IGT or type 2 diabetes had higher CRP levels, but TNFα, TNFR1, IL-6, and SAA were not significantly different between groups." (PMID 29951553, 2018). "Observed differences in total WBC counts and IL-6 levels (11%) were greater than those reported between non-cases and cases of CVD and non-cases and cases of type 2 diabetes in the Caerphilly study, respectively." (PMID 30096775, 2018). "Although we have no data on IL-6, it has been reported that IL-6 can stimulate insulin secretion through glucagon-like peptide-1 (GLP-1) production and secretion in animal models of type 2 diabetes." (PMID 28575103, 2017).
type 2 diabetes (continued). "In the present study, we found that metformin treatment has specific effects on cytokines (serum IL-6 and urinary MCP-1) as compared to the non-metformin (i.e., gliclazide, acarbose, or repaglinide) treatment type 2 diabetic patients." (PMID 27904436, 2016). "Consistent with this observational data, we previously found that almonds decreased IL-6 and CRP, and TNF-α in Chinese patients with type 2 diabetes but did not affect ICAM-1 or VCAM-1." (PMID 26080804, 2015). "In this study, we investigated the potential relationship of HDL-C levels, HDL subclasses, and hsPCR and IL-6 levels, two well-known markers of inflammation, in that cohort of CHD-free women with and without type 2 diabetes." (PMID 25258627, 2014). "The potential relationship between lipid profile, Apo-AI containing HDL subclasses distribution, and common inflammatory markers (hsCRP, IL-6) was examined in 160 coronary heart disease- (CHD-) free women with and without type 2 diabetes." (PMID 25258627, 2014). "As a whole, our results suggest that the effect of cytokines (IL-1β, IL-6 and TNF-α) on the incidence of type 2 diabetes might be mediated by other factors; they also suggest that these markers do not improve risk prediction as assessed by a validated type 2 diabetes risk score." (PMID 23251619, 2012). "As a result, our study elucidated that the cinnamon supplementation in the way of three grams per day for 8 weeks has not remarkable effect in reduction of NF-kB, SIRT1, hs-CRP, IL-6 and TNF-α plasma levels which have key role in atherogenicity in type 2 diabetes patients." (PMID 31901246, 2020). "Hepatic and plasma levels of triglyceride and cholesterol as well as glycerol, nonesterified fatty acids, IL-6, and TNF-α were potently increased during pregnancy in ethanol-fed E15.5 mice, whereas the adiponectin level, a predictive marker of type 2 diabetes (T2DM), was markedly decreased." (PMID 32572070, 2020). "In addition, anemic patients with type 2 diabetes without overt renal impairment presented a greater inflammatory state, with increased serum hsCRP, ESR, and IL-6 levels compared with non-anemic counterparts." (PMID 27043030, 2016). "Within adipose tissue, gene expression of the typically proinflammatory cytokines IL-6 and MCP-1 were increased 6 h following consumption of the meal, which supports previous findings from people with metabolic syndrome and non-obese relatives of people with type 2 diabetes." (PMID 26514561, 2017).